CYSLTR2 (cysteinyl leukotriene receptor 2)
Description:
Receptor for cysteinyl leukotrienes. The response is mediated via a G protein that activates a phosphatidylinositol-calcium second messenger system. Stimulation by BAY u9773, a partial agonist, induces specific contractions of pulmonary veins and might also have an indirect role in the relaxation of the pulmonary vascular endothelium. The rank order of affinities for the leukotrienes is LTC4 = LTD4 >> LTE4.
Synonyms: hGPCR21; CYSLT2; CYSLT2R; PSEC0146; CysLT(2); GPCR21; HG57; HPN321; KPG_011
Tractability: Small molecule: it belongs to a druggable protein family. Antibody: its Gene Ontology location is reachable by antibodies, with high confidence; UniProt places it where antibodies can reach, with medium confidence; UniProt predicts a signal peptide or a membrane-spanning region. PROTAC: a small molecule that binds it is known.
Target class: Leukotriene receptor; Small molecule receptor (family A GPCR); Membrane receptor; Lipid-like ligand receptor (family A GPCR); Family A G protein-coupled receptor
Chemical probes: HAMI3379
Gene: Protein-coding gene on chromosome 13 (48,653,709 to 48,711,227, forward strand). Ensembl gene ENSG00000152207.
Subcellular location: Cell membrane
Pathways (Reactome):
Signal Transduction: G alpha (q) signalling events; G alpha (s) signalling events; Leukotriene receptors
Disease: LTC4-CYSLTR mediated IL4 production
Gene Ontology:
Molecular function: protein binding; cysteinyl leukotriene receptor activity; galanin receptor activity; leukotriene receptor activity; G protein-coupled receptor activity
Biological process: immune response; neuropeptide signaling pathway; G protein-coupled receptor signaling pathway; leukotriene signaling pathway
Cellular component: plasma membrane; membrane
Genetic constraint (gnomAD): Loss-of-function variants: 0 observed, 1.33 expected, observed/expected ratio (o/e) 0, 90% interval 0 to 1.62. That is too few expected variants to judge how well the gene tolerates losing a copy. Missense variants: 398 observed, 430.28 expected, observed/expected ratio (o/e) 0.92, 90% interval 0.85 to 1. Synonymous variants: 179 observed, 167.31 expected, observed/expected ratio (o/e) 1.07, 90% interval 0.95 to 1.21.
Homologues: Orthologues: chimpanzee CYSLTR2 (97% identical), macaque CYSLTR2 (86% identical), dog CYSLTR2 (77% identical), guinea pig CYSLTR2 (70% identical), Caenorhabditis elegans gnrr-4 (17% identical). Paralogues in human: CYSLTR1 (32% identical), GPR17 (29% identical), LPAR6 (28% identical), LPAR4 (27% identical), F2R (25% identical), F2RL1 (24% identical), F2RL2 (23% identical), F2RL3 (23% identical), GPR18 (23% identical), GPR4 (22% identical), GPR65 (22% identical), P2RY10 (22% identical), and 4 more.
Diseases named in the same sentence as CYSLTR2 in open-access papers:
CYSLTR2 is named in the same sentence as 60 diseases in open-access papers, as found by Europe PMC text mining. Sharing a sentence is not in itself a finding about the gene and the disease. The quoted sentences say what the papers report.
uveal melanoma (20 papers, 2017 to 2025). A melanoma derived from melanocytes of the uveal tract. "The first mutation set encompasses the eight UM driver genes according to the TCGA study, divided into “uveal melanoma initiating mutations” (CYSLTR2, GNA11, GNAQ and PLCB4) and “second hit mutations with prognostic impact” (BAP1, EIF1AX, SF3B1 and SRSF2)." (PMID 39858540, 2025). "Their effect has not been precisely studied, but their exclusivity with the GNAQ, GNA11, and CYSLTR2 mutations and PLCβ4 being downstream of these proteins suggest that PLCβ4 mutations have a similar effect on the oncogenicity of uveal melanomas." (PMID 35158973, 2022). "Further analysis showed that the CYSLTR2 p.L129Q was clonal in both of these uveal melanomas, supporting an acquisition of this mutation early during tumour development." (PMID 33588787, 2021). "Taken together, these findings indicate that mutations in GNAQ, GNA11 and CYSLTR2 – all recurrently found in uveal melanomas – can also present as an independent somatic event in benign uveal nevi." (PMID 33588787, 2021). "Despite a lower level of significance, preferential expression of the mutant allele was also observed in two of the three CYSLTR2 mutant primary uveal melanomas from the TCGA cohort." (PMID 33588787, 2021). "One uveal melanoma metastasis (case MUM-20035) carried a copy number stable heterozygous CYSLTR2 mutation which was also hemizygously expressed at the RNA level." (PMID 33588787, 2021). "Moore and colleagues, analysing whole-genome and whole-exome sequencing data from 136 patients with uveal melanoma from multiple cohorts, found a previously undescribed mutation in CYSLTR2 encoding a p.Leu129Gln substitution." (PMID 31109147, 2019). "Activating mutations of CYSLTR2 (p.L129Q) in uveal melanoma are mutually exclusive and functionally equivalent to mutations in GNAQ/11 (p.Q209)." (PMID 31337866, 2019). "CYSLTR2 mutations occur in 3% of uveal melanoma patients, and 50% of cases associate with BAP1 mutations." (PMID 29156643, 2017). "Recently, the CYSLTR2 mutation was also detected in metastasising uveal melanomas." (PMID 33588787, 2021). "Expansion into publicly available bulk and single cell uveal melanoma sequencing data allowed to evaluate our findings in independent cohorts of primary and metastatic tumours and to study the role of wild-type CYSLTR2 in melanomas with a mutation in GNAQ, GNA11 or PLCB4." (PMID 33588787, 2021). "However, the observation has been made that the mutation and secondary alterations involving CYSLTR2 are found in all different molecular subtypes of uveal melanoma." (PMID 33588787, 2021). "We detected the CYSLTR2 mutation in 2/120 (~ 2%) screened primary uveal melanomas." (PMID 33588787, 2021). "Thus, GNAQ, GNA11, PLCB4, and CYSLTR2 form four modules of independent mutated uveal melanomas." (PMID 29156643, 2017). "PLCB4 mutations occur in approximately 5% of uveal melanoma and are mutually exclusive with GNAQ, GNA11, and CYSLTR2 mutations." (PMID 35158973, 2022). "A cohort of 120 archival primary uveal melanomas, treated by enucleation at the LUMC, was screened for the CYSLTR2 p.L129Q mutation." (PMID 33588787, 2021). "To gain insight into the regular transcriptional allelic balance of CYSLTR2, we studied RNA sequencing data from 77 CYSLTR2 wild-type primary uveal melanomas from the TCGA cohort." (PMID 33588787, 2021). "In the two CYSLTR2 mutant uveal melanomas from our Leiden cohort, we also evaluated the gene expression of both wild-type and mutant allele by digital PCR." (PMID 33588787, 2021). "In bulk RNA from CYSLTR2 wild-type uveal melanomas, we observed variable expression of CYSLTR2, with the highest levels in tumours with an immune gene expression signature." (PMID 33588787, 2021). "In the 77 CYSLTR2 wild-type tumours, eight cases presented with a copy number alteration involving the CYSLTR2 locus at chromosome 13q, making it an uncommon event in uveal melanoma." (PMID 33588787, 2021).
uveal melanoma (continued). "Publicly available bulk and single cell sequencing data were mined to further study mutant and wild-type CYSLTR2 in primary and metastatic uveal melanoma." (PMID 33588787, 2021). "The essential role of Gαq signalling in uveal melanoma tumorigenesis has been further supported by the discovery of rare but recurrent mutations in PLCB4 (p.D630) and CYSLTR2 (p.L129Q)." (PMID 33588787, 2021). "A study assessing data of 80 primary uveal melanoma samples in The Cancer Genome Atlas (TCGA) showed that higher expression of CYSLTR1 and CYSLTR2 genes were significantly associated with poorer disease-free survival and overall survival." (PMID 35008546, 2021). "Uveal melanoma (UM) has well-characterised somatic copy number alterations (SCNA) in chromosomes 1, 3, 6 and 8, in addition to mutations in GNAQ, GNA11, CYSLTR2, PLCB4, BAP1, SF3B1 and EIF1AX, most being linked to metastatic-risk." (PMID 32340176, 2020). "Among Uveal Melanoma (UM) driver mutations, those involving GNAQ or GNA11 genes are the most frequent, while a minor fraction of tumors bears mutations in the PLCB4 or CYSLTR2 genes." (PMID 31216772, 2019). "A total of 99 of these 118 patients (84%) had detectable ctDNA at baseline and on treatment, of whom 94 had mutations detected in one or more uveal melanoma genes (GNAQ, GNA11, SF3B1, PLCB4, CYSLTR2) at a variant allelic frequency of >0.3 at baseline and were included in the analyses." (PMID 36229663, 2022). "In this study, we examined the presence of CYSLTR2 mutations in non-malignant choroidal nevi and primary uveal melanomas." (PMID 33588787, 2021). "Similarly, in two of the three CYSLTR2 mutant primary uveal melanomas from the TCGA cohort preferential expression of the mutant allele was observed, while in all cases the wild-type allele was still present." (PMID 33588787, 2021). "Since both CYSLTR2 mutant tumours presented with chromosome 13q aberrations, we questioned whether such copy number alterations are common in CYSLTR2 mutant and wild-type uveal melanomas." (PMID 33588787, 2021). "Our findings suggest that CYSLTR2 is involved in both early and late development of uveal melanoma." (PMID 33588787, 2021). "In the TCGA cohort, mutations in GNAQ/11, CYSLTR2, and PLCB4 (2.5%) were found in 92.5%, 4%, and 2.5% of the samples, respectively, highlighting the involvement of G-protein signaling in the biology of uveal melanoma." (PMID 31357599, 2019). "However, constitutive activation of CysLTR2 in uveal melanoma acts as an oncogene." (PMID 35978827, 2022). "Importantly, the oncogenic alterations in uveal melanoma are not restricted to the CYSLTR2 mutation." (PMID 33588787, 2021). "A recent study reported recurrent mutations of G-protein-coupled receptor CYSLTR2 (cysteinyl leokotriene receptor 2) exclusively occurring in uveal melanoma patients not displaying GNAQ, GNA11, and phospholipase C, beta 4 (PLCB4) mutations (in about 40% of these patients)." (PMID 29156643, 2017). "The potential role of wild-type CYSLTR2 in GNAQ, GNA11 or PLCB4 mutant uveal melanomas was studied in publicly available bulk and single cell sequencing data." (PMID 33588787, 2021). "Tumors that did not harbor these mutations were found to have mutations in CYSLTR2, a G-protein-coupled receptor, in 4% of samples and in PLCB4, a downstream effector of GNAQ signaling in 2.5% of samples, highlighting the involvement of G-protein signaling in the biology of uveal melanoma." (PMID 31357599, 2019).
asthma (16 papers, 2008 to 2025). "For instance, a recent study describes the association between CYSLTR2 gene polymorphisms and asthma in humans." (PMID 39795883, 2024). "Further studies are required to examine the association between CYSLTR2 and response to asthma treatment." (PMID 39247132, 2024). "A significant association between the coding polymorphism 601A>G in CYSLTR2 and asthma was observed in a family-based study of asthmatics from Denmark and USA, with the G allele appearing to be less frequently transmitted to asthmatics." (PMID 27708579, 2016). "The associations of the CYSLTR1 and CYSLTR2 genes with atopy and asthma provided the rationale for studying the functional consequences of these variants with respect to agonist and their possible contribution to the atopy phenotype." (PMID 27990118, 2016). "The putative co-inheritance of CYSLTR1 and CYSLTR2 variants suggest a mode of asthma inheritance that is the result of epistasis." (PMID 27990118, 2016). "The association of CYSLTR2 and asthma was replicated in two subsequent studies and two functional studies showed potency of leukotriene D4 on the M202V variant was lower compared with the wild-type receptor." (PMID 18197984, 2008). "Furthermore, CysLTR2 is located on chromosome13q14.2-21.1, near a locus known to be associated with the risk of asthma in various population." (PMID 19840403, 2009). "Similarly, the contribution of CYSLTR1 and CYSLTR2 alleles may contribute additively or synergistically to asthma in association with other risk alleles and environmental factors." (PMID 27990118, 2016). "CYSLTR2 is a receptor to cysteinyl leukotrienes which are leukocyte chemo-attractants which act as bronchoconstrictors, and are important mediators of asthma." (PMID 39247132, 2024). "Inhibitors of CysLTR2 and CysLTR1 are currently being evaluated in Phase II trials as asthma treatments." (PMID 39247132, 2024). "The study of CYSLTR1 and CYSLTR2 gene variability in asthma, therefore, must be considered in the context of the genetic polymorphisms found within the synthesis pathway genes as well as genes that modify patient response to LTMs." (PMID 27990118, 2016). "CYSLTR2 is expressed in the lungs of asthmatics and its activation appears to contribute to antigen-induced bronchoconstriction in certain asthma populations." (PMID 27708579, 2016). "CysLTs exert their biological actions by binding two types of G-protein-coupled seven-transmembrane receptors: cysteinyl leukotriene receptor 1 (CysLTR1; MIM 300201), which is sensitive to the asthma drugs montelukast, zafirlukast and pranlukast and CysLTR2." (PMID 19840403, 2009). "CYSLTR2 maps to chromosome 13q14, approximately 300 kb from D13S153, which was reported linked to asthma in two studies." (PMID 18197984, 2008). "Finally, in the asthma vs. HC comparison, 9 SNPs were identified, with 2 associated with risk in the MS4A2 gene (rs573790 p = 0.001, OR = 1.70, CI 95% = 1.21-2.37), and 7 SNPs associated with protection in 4 genes (TBXAS1, FANCC, CYSLTR2, and PTGER3)." (PMID 30254660, 2018). "In the last comparison asthma vs. control group we detected seven SNPs in four genes (TBXAS1, FANCC, CYSLTR2, and PTGER3)." (PMID 31936183, 2020). "Cysteinyl leukotrienes are bronchoconstrictors and proinflammatory mediators of the asthma response that act through two G protein-coupled receptors: cysteinyl leukotriene receptor-1 (CYSLTR1) and CYSLTR2." (PMID 18197984, 2008).
breast carcinoma (9 papers, 2011 to 2023). "High CysLTR2 expression is correlated with a good prognosis in patients with colorectal cancer and breast cancer." (PMID 35978827, 2022). "In another study, aggressive CYSLTR2 negative breast cancer cells (MDA-MB-231) exhibited a decrease in migratory capacity after CYSLTR2 transfection which is associated with a reduction in metastatic potential." (PMID 27475906, 2016).
colon cancer (9 papers, 2010 to 2022). "In the current study, we also found a positive correlation between the CYSLTR2 and the expression of miR-125b in the colon cancer." (PMID 35401882, 2022). "Then, in TCGA-COAD, the CYSLTR2 showed low expression in colon tumors as compared to the corresponding normal tissues, suggesting that it may act as a tumor suppressor." (PMID 35401882, 2022). "The role of CYSLTR2 in myelomagenesis is still unknown although its dysregulation has been shown to facilitate cell proliferation and migration of colon cancer cells via CysLT signaling." (PMID 28458781, 2017). "An increased expression of CYSLTR1 receptor protein was described in gastrointestinal and urological malignancies before, whereas a loss of CYSLTR2 protein expression was shown in colon cancer cells compared to non-malignant intestinal cells." (PMID 27475906, 2016).
colorectal cancer (9 papers, 2011 to 2025). A primary or metastatic malignant neoplasm that affects the colon or rectum. "The expression of CYSLTR2 has also significantly been downregulated in multiple myeloma, melanoma, and colorectal cancer, which reveals its tumor suppressor function in other cancers also." (PMID 35401882, 2022). "We and others have shown that colorectal cancer patients with elevated cysteinyl leukotriene receptor 2 (CysLT2R) and 15-hydroxyprostaglandin dehydrogenase (15-PGDH) levels exhibit good prognoses." (PMID 32814764, 2020). "With respect to the CYSLTR2 function, a study on 329 colorectal cancers showed a more favorable prognosis for patients with high nuclear CYSLTR2 staining in combination with low nuclear CYSLTR1 receptor." (PMID 27475906, 2016).
melanoma (7 papers, 2020 to 2025). A malignant, usually aggressive tumor composed of atypical, neoplastic melanocytes. "At the RNA level, the CYSLTR2 allelic imbalance was skewed even further towards the mutant: in both melanomas hardly any expression of the wild-type allele was observed." (PMID 33588787, 2021). "All these melanomas were wild-type for CYSLTR2 and the majority carried mutations in GNAQ, GNA11 or PLCB4." (PMID 33588787, 2021). "In mutant melanomas, the relative gene dosage of the CYSLTR2 mutant allele may be further increased during (metastatic) progression of the tumour." (PMID 33588787, 2021). "At the RNA level, further silencing of wild-type and preferential expression of mutant CYSLTR2 was identified, which was also observed in two CYSLTR2 mutant primary melanomas and one metastatic lesion from other cohorts." (PMID 33588787, 2021). "In the melanomas, secondary, subclonal CYSLTR2 alterations shifted the allelic balance towards the mutant." (PMID 33588787, 2021). "In conclusion, our findings strongly nominate the rare CYSLTR2 p.L129Q mutation as an early oncogenic event in GNAQ and GNA11 wild-type uveal nevi and melanomas." (PMID 33588787, 2021). "As demonstrated in UMM066, CYSLTR2 expression was found in melanoma cells that also presented with high expression of pigmentation genes (MITF and TYR) and marker genes of MAPK (Mitogen-Activated Protein Kinase) pathway activation (MPAS)." (PMID 33588787, 2021). "In CYSLTR2 wild-type primary melanomas from the TCGA cohort, alterations involving chromosome 13q were uncommon and allelic balance was maintained in informative cases." (PMID 33588787, 2021). "Using single cell RNA data, we confirmed that wild-type CYSLTR2 is mainly expressed by melanoma cells." (PMID 33588787, 2021). "In the CYSLTR2 mutant melanomas, we further assessed the genetic heterogeneity within tumours and investigated the allelic balance of CYSLTR2 at the RNA level." (PMID 33588787, 2021). "In CYSLTR2 wild-type melanomas, high expression of CYSLTR2 correlated to tumour inflammation, but expression originated from melanoma cells specifically." (PMID 33588787, 2021). "However, in both melanomas secondary copy number alterations of the CYSLTR2 locus (chromosome 13q) were observed as well: PUM-1 showed loss of the wild-type allele, while in PUM-2 the mutant allele was gained." (PMID 33588787, 2021). "Analysis of a melanoma cell-rich area of the primary tumour, obtained by microdissection (PUM-1B), was specified to the single-amplicon assays (CYSLTR2 mutation and SNP assays on chromosome 3p and 13q) to prevent biases in DNA availablity due to degradation of FFPE-based input material." (PMID 33588787, 2021). "Overall, the large majority of CYSLTR2 expression originated from melanoma cells." (PMID 33588787, 2021). "In exceedingly difficult cases, molecular and genomic analysis can also be beneficial, as melanoma arising in blue nevi do not typically exhibit BRAF mutations, but rather GNAQ, GNA11, PLCB4, or CYSLTR2 mutations." (PMID 40843873, 2025). "It was however notable that the allelic balance of CYSLTR2 could not be studied in all samples, as CYSLTR2 expression varied largely between the melanomas." (PMID 33588787, 2021).